CYP2D6 (cytochrome P450 family 2 subfamily D member 6 (gene/pseudogene))
Diseases named in the same sentence as CYP2D6 in open-access papers (continued):
Sharing a sentence is not in itself a finding about the gene and the disease.
Obesity (11 papers, 2014 to 2025). Accumulation of substantial excess body fat. "Obesity is also associated with increased clearance of compounds metabolized by CYP2D6." (PMID 24647036, 2014). "BMI in our studied population showed a direct relationship with the transcriptional changes (downregulated) observed on selected genes (APC, ARNT, CYP2D6, LEPR, LRP12, and MYC), all of which are closely linked to the development of cancer or obesity." (PMID 35420343, 2022). "While early studies identified obesity, hyperandrogenemia and high levels of serum anti-Müllerian hormone as predictors for non-response, polymorphisms of CYP2D6 were additionally identified to alter drug disposition and response." (PMID 36559098, 2022). "On one hand, the increased activity of cytochrome P450 (CYPs) (CYP2C9, CYP1A2, CYP2E1, and CYP2D6) in individuals with obesity could augment generation of toxic metabolites." (PMID 34040524, 2021). "Moreover, we observed a significant positive correlation between CYP2D6 expression and BMI, which could support the literature data on increased CYP2D6 activity in obesity." (PMID 40359692, 2025). "Several potential functional genes, including CHAF1A, CEP192, ULK4, CYP2D6, AS3MT, and WARS2, were identified as common genetic factors linking obesity and IS." (PMID 39734234, 2024). "The identification of CHAF1A, CEP192, ULK4, CYP2D6, AS3MT, and WARS2 as potential functional genes common to both obesity and IS enriched our understanding of their genetic interplay, potentially advanced our grasp of their pathogenesis and therapeutic targets." (PMID 39734234, 2024).
respiratory depression (11 papers, 2015 to 2025). A decrease in ventilation secondary to impaired signals from the central nervous system. "When treated with opioids, such as codeine and tramadol, CYP2D6 UMs generate increased amounts of active metabolites, leading to a substantially increased risk of severe opioid toxidrome with respiratory depression even at labeled dosage regimens." (PMID 39540424, 2024). "Codeine is a notable CYP2D6 substrate, and individuals who are poor metabolizers will experience minimal analgesia while ultrarapid metabolizers will be at significant risk for respiratory depression and mortality." (PMID 34200695, 2021). "The safety of tramadol in children has been questioned since the mid-2010s, as respiratory depression induced by tramadol has been associated with overdosing but also with CYP2D6 UM phenotypes." (PMID 29556194, 2018). "CYP2D6*1*1 × N and CYP2D6*1/*2 × N alleles are denoted to be ultra-rapid metabolizers and might increase the risk of respiratory depression." (PMID 32708157, 2020). "In the PM group, a high risk of side effects due to tramadol, such as serotonin syndrome, can be expected; and in the UM group, a high risk of μ-opioid receptor-related side effects, such as respiratory depression, can be expected relative to other CYP2D6 genotypes." (PMID 31744222, 2019). "Conversely, CYP2D6 ultra-rapid metabolizers, who have more than two functional copies of the CYP2D6 gene, are able to generate excess morphine and are at risk for toxicity, including respiratory depression and death." (PMID 29099060, 2017). "Thus, in the situation in space, hydrocodone should be avoided in astronauts genotyped as CYP2D6 ultrarapid metabolizers because of a higher risk for hydromorphine induced respiratory depression." (PMID 26489089, 2015). "The principal sources of analgesia and respiratory depression originate from codeine transformation into morphine in the liver, primarily facilitated by CYP2D6, and its activity varies among individuals due to genetic polymorphisms." (PMID 38539313, 2024). "The codeine label also includes black box warnings stating that respiratory depression and death have occurred in children who received codeine following tonsillectomy and/or adenoidectomy, and that CYP2D6 inhibitors may impact drug response." (PMID 29099060, 2017). "Another consideration is drug interactions—CYP2D6 inhibitors (like paroxetine) can phenocopy a poor metabolizer, causing drug buildup; such interactions in an OSA patient on opioids could precipitate unexpected respiratory depression." (PMID 40649133, 2025).
serotonin syndrome (10 papers, 2013 to 2026). Serotoninergic syndrome is characterized by an excess of serotonin in the central nervous system, associated with the use of various agents, including selective serotonin reuptake inhibitors (SSRIs). "This is a complex interaction, which leads to decreased plasma concentrations of the active metabolite of tramadol (M1) because of CYP2D6 inhibition by paroxetine, and also an increased risk of serotonin syndrome." (PMID 35362214, 2022). "Therefore, there is the possibility of respiratory depression caused by serotonin syndrome, but confounders contributing to respiratory depression, which cannot be considered in this study, may exist in CYP2D6 inhibitor concomitant users." (PMID 38399420, 2024). "CYP2D6 inhibition not only reduces the formation of M1, it also increases tramadol parent drug plasma concentrations, which may be associated with an increased risk of the potentially life-threatening, dose-dependent serotonin syndrome." (PMID 38399420, 2024). "CYP2D6 poor metabolizers and those with deficient serotonin (5-HT) uptake who take tramadol may be at risk for serotonin syndrome (SS), which begins within 24 hours of starting or increasing a 5-HT reuptake or CYP2D6 inhibitor (Beakley, Kaye, & Kaye, 2015; Houlihan, 2004; Leppert, 2009)." (PMID 30310721, 2017). "In fact, ginseng toxicity mainly comes from drug interactions with cytochromes P450 (CYPs) CYP3A4 and CYP2D6 inhibitors and serotoninergic drugs, intensifying sedative effects or inducing cognitive disorders or a serotonin syndrome." (PMID 33066617, 2020). "While aripiprazole alone is not a common cause of serotonin syndrome, its metabolism via CYP2D6 and CYP3A4 suggests a possible interaction with residual DXM metabolites, which may have delayed serotonin clearance and increased the risk of toxicity." (PMID 40673125, 2025). "Several case reports have documented serotonin syndrome in individuals who overdosed on DXM, especially when combined with CYP2D6 inhibitors, such as fluoxetine or paroxetine." (PMID 40673125, 2025). "Although it is not commonly associated with serotonin syndrome, its metabolism via CYP2D6 and CYP3A4 suggests a possible interaction with DXM, particularly in poor metabolizers of CYP2D6." (PMID 40673125, 2025).
Bradycardia (9 papers, 2018 to 2025). A slower than normal heart rate (in adults, slower than 60 beats per minute). "The results of our study indicate that CYP2D6 PMs have an increased risk of bradycardia and a lower minimum HR compared to NMs and phenoconverters." (PMID 36983598, 2023). "Metoprolol plasma concentrations can vary significantly depending on CYP2D6 activity and are associated with bradycardia in PMs." (PMID 33799547, 2021). "Studies have observed that homozygotes and heterozygotes for the SNP rs16947 (CYP2D6 *2) may increase the risk of developing bradycardia induced by timolol, and that the SNP rs769258 (CYP2D6 *35 duplication-negative) is notably more prevalent in Caucasian UMs." (PMID 40142989, 2025). "Systemic side effects, such as bradycardia or arrhythmia, were reported in nine patients (8.26%), of whom five were also receiving systemic medication metabolized by CYP2D6." (PMID 40142989, 2025). "This study found that CYP2D6 PMs taking metoprolol had a significant increase in the incidence of symptomatic bradycardia compared to genotypic NMs." (PMID 36983598, 2023). "This study further supports the role of genetic testing in precision medicine to help individualize patient care as CYP2D6 poor metabolizers taking metoprolol were found to have an increase in bradycardia." (PMID 36983598, 2023). "Anecdotally, we have noticed bradycardia seems more common in our patients that are CYP2D6 PMs or those taking phenoconverting medications." (PMID 36983598, 2023). "Nevertheless, these guidelines do not recommend testing for CYP2D6 alleles before metoprolol use or applying any changes in dosing unless the occurrence of symptomatic bradycardia." (PMID 38108069, 2023).
COVID-19 (8 papers, 2020 to 2024). A disease caused by infection with severe acute respiratory syndrome coronavirus 2. "It was demonstrated that the CYP2D6 variant is associated with the hydroxychloroquine metabolic ratio, which was recently used in COVID-19 treatment." (PMID 36553620, 2022). "The clinical course of the disease has been challenged by the interaction of three genetic polymorphisms, all affected by COVID-19: first is the CYP2D6 enzyme system, second is the HO-1 anti-inflammatory gene, and third the ACE and ACE-2 enzyme systems." (PMID 32708430, 2020). "The present study explores the effect of Ashwagandha and AYUSH-64 on important human CYP enzymes (CYP3A4, CYP2C8, and CYP2D6) to assess their interaction with remdesivir, a drug used for COVID-19 management during the second wave." (PMID 36313313, 2022). "Future combination of Heme arginate and LPV/RTV or drugs that are not metabolized by CYP2D6/3A4 might have a synergy as an efficacious dual drug-therapy to counteract the severe inflammation caused by COVID-19." (PMID 32708430, 2020). "Most drugs used to treat COVID-19 are metabolized by cytochrome P450 (CYP) enzymes, primarily CYP2D6." (PMID 36553620, 2022). "In carriers of CYP2D6*4 (AA), HCQ is poorly metabolized which results in reduced formation of desethyl HCQ, thus probably diminishing the efficiency of HCQ in preventing COVID-19 viruses from entering cells." (PMID 35745658, 2022). "The majority of the medications used in the treatment of COVID-19 are metabolized by cytochrome P450 (CYP) enzymes, primarily CYP2D6." (PMID 32708430, 2020). "The CYP2D6 and CYP2C19 genes were responsible for most treatment modifications, and the medications most often affected were ondansetron, oxycodone, and clopidogrel, commonly given to patients with COVID-19." (PMID 36553620, 2022). "CYP1A2, CYP2D6, and CYP2C19 metabolize fluvoxamine and its therapeutic concentrations could be significantly impacted by varying miR-155 levels, which differ between young, healthy individuals and older individuals with co-morbidities in COVID-19." (PMID 38862591, 2024). "HCQ may also inhibit CYP2D6, interacting with a variety of different COVID-19 and non-COVID-19 medications." (PMID 33355896, 2021).
G6PD deficiency (8 papers, 2017 to 2024). An X-linked genetic condition caused by alterations in the gene G6PD that result in moderately to severely decreased activity levels of the enzyme glucose-6-phosphate dehydrogenase. "The prevalence of anaemia was not significantly different between groups on day 3 but was significantly different on day 7 with all the patients with G6PD deficiency and those with both reduced CYP2D6 and G6PD deficiency being anaemic." (PMID 35279143, 2022). "The prevalence of reduced CYP2D6 enzyme activity among the enrolled patients was 21.0% (33/157) while that of G6PD deficiency was 12.7% (20/157)." (PMID 35279143, 2022). "Prevalence of G6PD deficiency and CYP2D6 polymorphisms in a population are thus important considerations for public health interventions involving the deployment of 8-aminoquinoline drugs like PQ." (PMID 29558929, 2018). "Phenotypic and genotypic analyses both detected low prevalence of G6PD deficiency and the CYP2D6*4 variants." (PMID 29558929, 2018). "South Africa has previously (1940s–1980s) reported fewer cases of G6PD deficiency (5.3%) and CYP2D6 (2.6%) mutations compared to its neighbouring countries, most likely a consequence of genetic differences among the distinct ethnic groups." (PMID 29558929, 2018). "In sub-Saharan Africa, prevalence of G6PD deficiency is estimated to range between 5 and 37.5%, and CYP2D6 allele frequencies range from 1 to 33%." (PMID 29558929, 2018). "This is the first study employing genotyping to evaluate locally relevant G6PD deficiency and CYP2D6 variants in a pre-elimination setting of South Africa." (PMID 29558929, 2018). "Due to a paucity of current data, regionally-relevant evidence of G6PD deficiency and CYP2D6 variant metrics are needed." (PMID 29558929, 2018). "Of the patients with haemoglobinuria, 3.0% (1/33) had reduced CYP2D6 activity, and 5.0% (1/20) had G6PD deficiency, and the difference in the prevalence between CYP2D6 (x2 = 1.29, p = 0.257) or G6PD (x2 = 0.10, p = 0.751) status was not statistically significant." (PMID 35279143, 2022). "Thus, considering the observed P. vivax circulation in different regions of Cameroon, larger studies assessing G6PD deficiency prevalence and CYP2D6 polymorphism frequency in the whole country are necessary in order to ensure a safer therapeutic use of PQ." (PMID 28196496, 2017). "Out of 11 participants with G6PD deficiency and normal CYP2D6 enzyme activity, 5 (45.5%) had acute haemolysis, whereas none (0/9) of participants with G6PD deficiency and reduced CYP2D6 had acute haemolysis (Fishers’ test, p = 0.038)." (PMID 35279143, 2022).
hyperprolactinemia (8 papers, 2017 to 2023). Abnormally high level of prolactin in the blood. "As a consequence, ASD children who are CYP2D6 PMs or IMs might be at higher risk of developing hyperprolactinemia when treated with risperidone." (PMID 38375208, 2023). "One study explored the impact of CYP2D6 polymorphisms on the prevalence of risperidone-induced adverse effects, including hyperprolactinemia, revealed that the poor-metabolizer phenotype influenced the frequency of adverse effects and poor treatment compliance." (PMID 33535976, 2021). "Strong associations of some pharmacokinetic/pharmacodynamic gene variants, e.g., CYP2D6 and DRD2, with risperidone-induced hyperprolactinemia have been found in children with ASD, but such strong genetic associations have not been found directly for aripiprazole in ASD." (PMID 38375208, 2023). "Strong associations of some pharmacokinetic/pharmacodynamic gene variants, e.g., CYP2D6 and DRD2, with risperidone-induced hyperprolactinemia have been found in children with ASD, but such genetic associations have not been found directly for aripiprazole in ASD." (PMID 38375208, 2023). "While the findings regarding movement abnormalities and lack of therapeutic effect concur with existing evidence, AIWG and hyperprolactinemia were not consistently linked with CYP2D6 impairments." (PMID 35745668, 2022). "Second, although our findings were in accordance with previous reports demonstrating no influence of CYP2D6 variation on PRL levels in antipsychotic-induced hyperprolactinemia, some candidate genes associated with changes in PRL were not included in our study." (PMID 36313772, 2022). "However, the relationship between hyperprolactinemia and CYP2D6 phenotype is unclear." (PMID 37693320, 2023). "The relationship between CYP2D6 and hyperprolactinemia (a possible adverse effect of RIS) appears to be U-shaped, with a tendency (though not consistently replicated) for both extremes of CYP2D6 metabolic phenotype (i.e., PMs and UMs) to show an association with hyperprolactinemia." (PMID 33363564, 2020).
autoimmune hepatitis (7 papers, 2016 to 2025). Hepatitis caused by autoantibodies. "Cytochrome P450 (CYP2D6) is the target of liver kidney microsomal autoantibody type 1 (LKM1) in autoimmune hepatitis (AIH) type 2." (PMID 39057754, 2024). "In patients with autoimmune hepatitis, autoantibodies can frequently be detected targeting cytochrome P450 2D6 (CYP2D6)." (PMID 33615312, 2020). "In this study, we investigated the effect of costunolide in two murine models of AIH: Concanavalin A (ConA)-induced acute immune-mediated hepatitis and human Cytochrome P4502D6 (CYP2D6) plasmid injection-induced chronic autoimmune hepatitis." (PMID 37163367, 2023). "In autoimmune hepatitis (AIH), autoantibody LKM-1 from B cells can target and recognize CYP2D6 on hepatocytes, which may be directly involved in autoimmune liver injury." (PMID 40761743, 2025).
diabetes (7 papers, 2020 to 2024). "Therefore, this study aims to examine the association between CYP2C19 and CYP2D6 metabolic phenotypes and the risk of diabetes mellitus in UK Biobank participants taking antidepressants and antipsychotics." (PMID 34828364, 2021). "In conclusion, the findings of this study clearly show that a large fraction of persons with diabetes are exposed to drugs or drug combinations for which there exist PGx-based dosing guidelines related to CYP2D6, CYP2C19, and SLCO1B1." (PMID 34577599, 2021). "Among participants with diabetes who were taking venlafaxine, CYP2D6 poor metabolizers had higher HbA1c levels compared to normal metabolizers (mean differences: 10.15 mmol/mol; p < 0.001." (PMID 34828364, 2021). "Among participants with diabetes who were taking fluoxetine, CYP2D6 intermediate metabolizers and decreased HbA1c, compared to normal metabolizers (mean difference −7.74 mmol/mol; p = 0.017)." (PMID 34828364, 2021). "For several of the antidepressants investigated, we consistently found that the interaction of diabetes status and CYP2D6 and CYP2C19 metabolic phenotype is statistically significant." (PMID 34828364, 2021). "Our results indicate that the impact of genetic variation in CYP2D6 differs depending on diabetes status." (PMID 34828364, 2021). "In participants taking venlafaxine (SNRI), we found that, amongst people with diabetes, poor metabolizers for CYP2D6 had higher HbA1c than normal metabolizers (mean difference: 10.15mmol/mol; 95% CI (2.63,17.67); p = 0.008)." (PMID 34828364, 2021). "CYP1A2 and CYP2C9 activities showed a trend to slightly increase in subjects with diabetes, but activities of CYP2D6 and CYP2E1 were unaltered." (PMID 32290519, 2020). "Our findings add support to this theory, suggesting that decreased CYP2D6 metabolism may in fact be somewhat beneficial for patients with diabetes who take fluoxetine." (PMID 34828364, 2021). "Several studies have demonstrated that CYP2D6 activity is unaltered by diabetes." (PMID 32290519, 2020). "The frequency of DGI as recently reported for CYP2D6, CYP2C19 and SLCO1B1 further implies that a significant proportion of persons with diabetes will have phenotypes for which actions in principle should be taken regarding dose adjustment or avoidance of the given drugs." (PMID 34577599, 2021).